KLF4 (KLF transcription factor 4)
Diseases named in the same sentence as KLF4 in open-access papers (continued):
Sharing a sentence is not in itself a finding about the gene and the disease.
bladder cancer (49 papers, 2011 to 2025). "The role of CK2 in controlling the activity of krueppel-like factor 4 (KLF4)—a transcription factor implicated in bladder cancer proliferation—is regulated by tumour suppressor p21." (PMID 34680478, 2021). "It has been reported that METTL3 can cause the m6A modification of KLF4 mRNAs in bladder cancer." (PMID 38879589, 2024). "Interestingly, KLF4 inhibition has been shown to promote invasion and migration in vitro and linked to poor progression and early recurrence in bladder cancer." (PMID 29599914, 2018). "It is reported that KLF4 also regulates the Warburg effect, but the precise role and underlying signaling cascade of KLF4 in the Warburg effect in bladder cancer remain unclear." (PMID 28380435, 2017). "Therefore, KLF4 appears to be negatively associated with bladder cancer progression, and paradoxically, KLF4 may play a facilitating role in advanced BC." (PMID 37031197, 2023). "In bladder cancer, miR‐145 interferes with the Warburg effect by inhibiting the KLF4/PTBP1/PKMs pathway in bladder cancer cells to suppress tumour growth." (PMID 40579921, 2025). "The METTL3–YTHDF2–m6A signaling axis orchestrates the turnover of transcripts encoding the kruppel Like factor 4 (KLF4) and SET domain containing 7 (SETD7), thereby fueling the malignant proliferation of bladder cancer cells." (PMID 40986143, 2025). "MiR-145 disrupts the Warburg effect by inhibiting the KLF4/PTBP1/PKMs pathway in bladder cancer cells, leading to significant inhibition of cell growth." (PMID 40689207, 2025). "p21 depletion converts KLF4 from a cell cycle inhibitor to a promoter of bladder cancer cell proliferation." (PMID 36171897, 2022). "Recent studies showed that METTL3-mediated m6A hypermethylation promotes the progression of bladder cancer by regulating SETD7/KLF4 mRNA expression, pri-mrR221/222 maturation and AFE4/NF-κB/MYC signaling network activation." (PMID 35945641, 2022). "In bladder cancer, Notch-1 regulates the proliferation and differentiation of cancer cells by inhibiting the expression of KLF4." (PMID 34367275, 2021). "Xie and colleagues have determined that the METTL3/YTHDF2 m6A axis directly degraded the mRNA of the transcription factor KLF4, contributing to the progression of bladder cancer." (PMID 34774019, 2021). "Previous studies prioritized SERPINE1 as a target of mir-143/145 in bladder cancer, as well as mir-34a in liver cancer, regulating KLF4." (PMID 34494932, 2021). "YTHDF2 recognizes these m6A modifications and degrades the SETD7 and KLF4 mRNAs, leading to bladder cancer progression." (PMID 32765970, 2020). "Although signaling elicited by the stem cell factors SOX2, OCT4, KLF4, and MYC has been associated with cancer progression in several tumors, it has remained unclear how these signaling molecules mediate bladder cancer progression." (PMID 32427884, 2020). "KLF4 expression is downregulated in several malignancies like gastric cancer, colorectal cancer, and bladder cancer where it mainly functions as a tumor suppressor gene." (PMID 31245293, 2019). "It has been shown that transduction of the KLF4 gene using adenoviral vectors decreased proliferation and induced apoptosis of bladder cancer cells." (PMID 31245293, 2019). "We demonstrate that the expression of KLF4 was increased in bladder cancer (BC) cells from patients." (PMID 28380435, 2017). "In bladder cancer cells, miR-145 is down-regulated and its mimics reduce the Warburg effect by directly silencing kruppel like factor 4 (KLF4)." (PMID 28832500, 2017). "Furthermore, luciferase assays demonstrated that miR-145 directly binds to the 3′UTR of KLF4, and that Warburg effect-related genes, such as PTBP1 and PKMs, are regulated by bladder cancer cells transfected with miR-145 or siR-KLF4." (PMID 40689207, 2025). "This suggests that IGF2BP3 may not only promote EMT by inhibiting KLF4, but also prevent bladder cancer cell differentiation." (PMID 38504159, 2024).
bladder cancer (continued). "HOXD10 and KLF4 were identified as direct targets of miR-10b in bladder cancer." (PMID 37627900, 2023). "MMP14 and E-cadherin may be the downstream targets of HOXD10 and KLF4 in the miR-10b-mediated suppression of bladder cancer metastasis." (PMID 37627900, 2023). "Furthermore, KLF4 is acetylated in a p21-dependent manner to inhibit bladder cancer cell growth as a tumor suppressor." (PMID 36171897, 2022). "Three other pathways are also associated with METTL3 upregulation in bladder cancer, including the METTL3 -CDCP1 (CUB Domain Containing Protein 1), METTL3-ITGA6(Integrin Subunit Alpha 6), and METTL3/YTHDF2-SETD7/KLF4(SET Domain Containing Lysine Methyltransferase 7/ Kruppel Like Factor 4) m6A axes." (PMID 32765970, 2020). "Furthermore, we examined immunohistochemical stainings to evaluate KLF4 expression in KLF4 positive clinical samples by Western blot analysis in bladder cancer (5 samples)." (PMID 28380435, 2017). "In the current study, we examined whether or not miR-145 could affect the regulation of the Warburg effect through silencing KLF4 in bladder cancer cells." (PMID 28380435, 2017). "Their results indicated that deacetylated KLF4 can act as an oncogene accelerating bladder cancer proliferation; on the contrary, acetylation of KLF4 performs as a tumor suppressor, which may be a good target for bladder cancer therapy." (PMID 27594736, 2016). "Therefore, the inhibition of the miR-10b/HOXD10/MMP14 and miR-10b/KLF4/E-cadherin axes may offer potential therapeutic targets for metastatic bladder cancer." (PMID 37627900, 2023). "Interestingly, the pathways of KLF4 is a possible link between obesity and bladder cancer." (PMID 31817583, 2019). "Recently, studies have reported that METTL3 is highly expressed in bladder cancer and degrades SETD7 and KLF4 mRNAs combined with the m6A reader YTHDF2." (PMID 37259333, 2023). "M6A readers (YTHDF2, IGF2BP1, and IGF2BP3) promote the progression of bladder cancer by stabilizing SETD7, KLF4, FSCN1, and MYC mRNA and regulating JAK/STAT signaling pathway activation." (PMID 35945641, 2022). "In bladder cancer, the mutual interaction between METTL3 and YTHDF2 induced the degradation of SETD7 and KLF4 mRNA in the proliferation and metastasis process." (PMID 34996459, 2022). "Luckily, it was found that YTHDF2 was up-regulated in bladder cancer and the up-regulated YTHDF2 advanced the progression of bladder cancer through cooperating with METTL3 and directly degrading the mRNAs of SETD7 and KLF4 in an m6A dependent manner." (PMID 33593354, 2021). "YTHDF2 promotes the mRNA degradation of tumor suppressor genes SET domain containing lysine methyltransferase 7 (SETD7) and Kruppel Like Factor 4 (KLF4) by identifying METTL3-mediated m6A modification, thus inducing bladder cancer progression." (PMID 33692959, 2021). "It has been reported that the tumor suppressor KLF4, another member of the KLF family, could be regulated in an m6A-dependent manner in bladder cancer." (PMID 35311620, 2022). "Because factors in ESC signaling and iPSC reprogramming have been linked to tumor malignancy, we used the Cox’s proportional hazards model to analyze the link between SOX2, KLF4, MYC and OCT4 expression and recurrence-free survival outcome for bladder cancer patients." (PMID 32427884, 2020). "Moreover, miR-145 directly binds to 3'UTR of KLF4 and negatively regulates Warburg effect by silencing KLF4 and PTB1 in bladder cancer cells, resulting in significant cell growth inhibition." (PMID 29299177, 2017). "Similarly, in our previous study, we also found that the expression of METTL3 and YTHDF2 was up‐regulated in bladder cancer and showed that METTL3 inhibited the expression of SETD7 and KLF4 in an m6A‐YTHDF2‐dependent manner to further promote the proliferation and metastasis of bladder cancer." (PMID 32808488, 2020). "We found that SOX2, but not OCT4, KLF4, or MYC expression, correlates with poor prognosis and histologic differentiation in bladder cancer." (PMID 32427884, 2020).
glioma (39 papers, 2007 to 2025). A benign or malignant brain and spinal cord tumor that arises from glial cells (astrocytes, oligodendrocytes, ependymal cells). "This study aimed to explore the function of CHRM3-AS2, a rarely reported lncRNA, in glioma, as well as the underlying mechanisms involving miR-370-5p/KLF4." (PMID 35359381, 2022). "Given the combination of interactions of CHRM3-AS2 and miR-370-5p with KLF4 expression, we suggest that miR-370-5p-mediated KLF4 expression is part of the underlying mechanism of action of CHRM3-AS2 on glioma cells." (PMID 35359381, 2022). "The expression of KLF4 has been found to be significantly repressed in human gliomas-associated vascular endothelial cells as compared with that found in non-neoplastic control vascular endothelial cells, suggesting that KLF4 is involved in an anti-angiogenic pathway." (PMID 17472751, 2007). "Colony formation and SA-β-gal staining assays revealed that KLF4 overexpression significantly enhanced cell proliferation, while reducing the extent of cellular senescence in glioma cells." (PMID 40181456, 2025). "Our rescue assays further confirmed that TRAF7 promotes glioma progression in a KLF4-dependent manner." (PMID 40181456, 2025). "Then the impact of KLF4 overexpression on glioma cell proliferation and senescence was assessed in the Hs683 and U251 cell lines." (PMID 40181456, 2025). "In a remarkable feedback loop, ITGB4 interacted with KLF4 and reduced its binding to E3 ligase VHL in glioma cells, thereby enhancing KLF4 stability and increasing KLF4 expression." (PMID 40034124, 2025). "A previous report showed that silencing of CHRM3-AS2 expression inhibited cell viability, colony formation, migration, and invasion and promoted apoptosis effects by targeting miR-370-5p/KLF4 in Glioma." (PMID 37641095, 2023). "In this study, KLF4 was found to be up-regulated in glioma cells, indicating a tumour-promoting potential." (PMID 35359381, 2022). "miR-92a overexpression promotes glioma cell proliferation through the KLF4 (Kruppel-like factor 4)/AKT/mTOR signaling pathway." (PMID 36479040, 2022). "Silencing of CHRM3-AS2 expression inhibited the malignant progression of glioma by regulating miR-370-5p/KLF4 expression." (PMID 35359381, 2022). "On the other hand, the underexpression of LINC-ROR is correlated with the mRNA expression levels of SOX11 and KLF4 in glioma." (PMID 33745265, 2021). "IL-8 transcript expression moreover positively correlated with KLF4 (Kruppel-like factor 4), c-Myc oncogene, and HIF2α, which are molecular hallmarks of glioma-initiating cells (GICs)." (PMID 32886667, 2020). "Simultaneously, we found that ITGB4 interacted with KLF4 and decreased its binding to the E3 ligase VHL in glioma cells, which subsequently enhanced KLF4 stability and increased KLF4 expression." (PMID 30658712, 2019). "Expression of KLF4 was almost non-detectable in 9L tumors, both in endothelial cells of tumor capilaries and in tumor cells, while U87-MG gliomas expressed low levels of KLF4 in tumor cells." (PMID 30837601, 2019). "We found that KLF4 overexpression promoted glioma growth as indicated by the increase in the size and weight of xenograft tumours." (PMID 30658712, 2019). "Expectedly, KLF4 mRNA level was inversely correlated with FOXO1 mRNA level in glioma tissue samples." (PMID 27835585, 2016). "Our findings indicated that FOXO1 down-regulation mediated by KLF4 confers to progression of glioma." (PMID 27835585, 2016). "Bioinformatics analysis and experimental results indicated that KLF4 transcriptionally repressed FOXO1 expression in glioma cells." (PMID 27835585, 2016). "KLF4 induced by PGI initiated by mesenchymal glioma cells, induces the self-renewal and tumorigenic potentials of glioma stem cells." (PMID 27835585, 2016). "We further confirmed the role of KLF4 in growth of glioma cells in vivo using nude mice with glioma xenografts." (PMID 27835585, 2016).
glioma (continued). "KLF4 mRNA level in the 39 fresh-frozen human primary glioma tissue samples with diverse grades was detected using qRT-PCR." (PMID 27835585, 2016). "KLF4 protein level was also inversely correlated with FOXO1 protein level in the glioma tissue samples." (PMID 27835585, 2016). "Compared with normal brain tissue samples, KLF4 protein level was significantly up-regulated in the majority of primary glioma tissue samples, with a greater increase in high-grade gliomas than in low-grade." (PMID 27835585, 2016). "More recently, Holmberg and colleagues showed that high grade gliomas coexpress pluripotency transcription factors Oct4, Sox2, Nanog and Klf4 together with mesodermal Brachyury and endodermal Sox17 transcription factors." (PMID 22276221, 2012). "Although our results indicate that the capacity of Sox3 to hinder differentiation is conserved between glioma cells and NSCs, further studies will be necessary to explain the exact role of Oct4, Nanog and Klf4 in gliomas." (PMID 21483788, 2011). "In view of the discovery of CHRM3-AS2/miR-370-5p/KLF4 axis in glioma cells, we suspected that CHRM3-AS2 silencing may exert inhibitory effects on glioma cells through regulating miR-370-5p/KLF4." (PMID 35359381, 2022). "The CHRM3-AS2/miR-370-5p/KLF4 axis involved in the progression of glioma may represent a potential therapeutic target." (PMID 35359381, 2022). "Importantly, silencing of CHRM3-AS2 expression inhibited the malignant progression of glioma through regulation of the miR-370-5p/KLF4 axis." (PMID 35359381, 2022). "KLF4 is supposed to be crucial for the integrity of the blood-tumor barrier because it enhances the promoter activities of tight junction proteins (TJPs), including ZO-1, occludin, and Claudin5 in the glioma endothelial cells." (PMID 32264912, 2020). "The binding assays suggested that ITGB4 could interact with KLF4 in glioma cells and they were co-localization in the cells." (PMID 30658712, 2019). "To evaluate the clinical relevance of the KLF4-ITGB4 axis, we first examined the expression of KLF4 in human glioma samples (n = 112; World Health Organization (WHO) grade II–IV) and nonneoplastic brain tissue samples (n = 8) by immunohistochemical (IHC) staining." (PMID 30658712, 2019). "The effect of KLF4 on cell invasion in glioma cells was determined using transwell assay." (PMID 27835585, 2016). "Moreover, KLF4 expression increase correlated with glioma progression and predicted a poorer overall survival of glioma patients." (PMID 27835585, 2016). "Additionally, we found that KLF4 expression frequently increased in glioma tissues and negatively correlated with FOXO1 expression." (PMID 27835585, 2016). "Additionally, the increase of KLF4 mRNA level in high-grade gliomas was greater than in low-grade gliomas." (PMID 27835585, 2016). "Furthermore, for the analysis of overall survival (OS), glioma patients group with high KLF4 protein level had significantly worse OS than the patients group with low KLF4 protein level." (PMID 27835585, 2016). "However, in contrast to NSCs glioma cells co-express neural proteins together with pluripotent stem cell markers, including the transcription factors Oct4, Sox2, Nanog and Klf4." (PMID 21483788, 2011). "In addition, CHRM3-AS2 targeted miR-370-5p/KLF4 in glioma cells." (PMID 35359381, 2022). "Therefore, according to the literature above, we wondered whether Sox2, Oct4, KLF4, Nanog, Lin28A and Lin28B contribute to glioma cell dedifferentiation in hypoxic environments." (PMID 34976166, 2022). "In addition, KLF4 is shown to regulate the integrity of blood-tumor barrier via enhancing the promoter activities of TJPs including ZO-1, occludin, and Claudin5 in the glioma endothelial cells." (PMID 32264912, 2020).
glioma (continued). "It is conceivable, that in gliomas high levels of HDAC4 expression in complex with MEF2 acts as transcriptional repressor of KLF4 and, consequently, of zonula occluden-1, claudin-5, and occludin gene expression, which may be another important component in the mechanism of BBB disruption in gliomas." (PMID 30837601, 2019). "In glioma, KLF4 directly binds to the ITGB4 promoter, promoting its transcription and contributing to increased expression of ITGB4 in glioma." (PMID 40034124, 2025). "For example, GKLF, also known as KLF4, showed a highly significant result and is known to be involved in the self-renewal of glioma stem cells and glioma-genesis through its interaction with ITGB4." (PMID 41007824, 2025). "Collectively, these studies unveil a novel feedback loop linking KLF4 and ITGB4 that contributes to the self-renewal of glioma stem cells and the development of gliomas." (PMID 40034124, 2025). "The transcription factor, KLF4 and ZKSCAN3, facilitate ITGB4 expression respectively in glioma and liver cancer by directly binding to its promotor." (PMID 35305660, 2022). "Overall, the mRNA levels of ACVR1, STAT3, WNT5A, KLF4 and DMC1 were obviously decreased in glioma samples with 1p19q codeletion compared to those in glioma samples without 1p19q codeletion." (PMID 36435765, 2022). "The data showed that IPS reprogramming factors and pluripotency-related genes (POU5F1, SOX2, KLF4, MYC and NOTCH1) were detected in almost all histologic types and grades of gliomas." (PMID 36435765, 2022). "Compared with HEB cells, glioma cells (U251, SHG-44, U87, and T98) exhibited significantly higher expression levels of KLF4 at both the mRNA and protein levels (P < 0.01)." (PMID 35359381, 2022). "Here, we found that KLF4 directly binds to the promoter of ITGB4, facilitating its transcription and contributed to ITGB4 increase in glioma." (PMID 30658712, 2019). "Taken together, our data suggests the existence of a positive feedback loop between KLF4 and ITGB4 that promotes GSC self-renewal and gliomagenesis, and also implicates ITGB4 as a valuable therapeutic target for glioma." (PMID 30658712, 2019). "Exposure to temozolomide (TMZ) increases the expression of KLF4 and reduces the expression of Nanog and OCT4 in glioma cells, indicating that stem cell factors, especially KLF4, play pivotal roles in GSCs." (PMID 31653034, 2019). "Quantitative RT-PCR analysis showed decreased expression of Nanog, Sox2, KLF4, nestin and CD133, together with increased expression of the differentiation marker glial fibrillary acidic protein (GFAP) in AP-2α overexpressing glioma cells." (PMID 31534499, 2019). "Glioma CSCs as neural stem cells (NSCs), express stem cell markers such as CD133, SOX2, KLF4, and Nestin." (PMID 31661894, 2019). "At the same time, the expression of LncRNA-ROR was negatively correlated with the expression of stem cell factor KLF4, which indicated that LncRNA-ROR played an inhibitory role in the proliferation and self-renewal of glioma stem cells." (PMID 28245841, 2017). "Given that FOXO1 inhibits glioma cells invasion and growth, and that KLF4 transcriptionally inhibits FOXO1 expression, we here also observed the effects of KLF4 on invasion and growth in glioma cells." (PMID 27835585, 2016). "For example, in glioma, the downregulation of lncRNA–ROR promoted the proliferation of cancer cells and the formation of a sphere of stem cells with the down expression of stem cell factor KLF4." (PMID 35338348, 2022). "Thus, our study reveals that a novel feedback loop exists between KLF4 and ITGB4, which contributes to GSC self-renewal and glioma tumourigenesis." (PMID 30658712, 2019). "Further mechanistic studies revealed that KLF4, an important transcription factor, directly binds to the promoter of ITGB4, facilitating its transcription and contributing to increased ITGB4 expression in glioma." (PMID 30658712, 2019).